PTK7 (protein tyrosine kinase 7 (inactive))
Diseases named in the same sentence as PTK7 in open-access papers (continued):
Sharing a sentence is not in itself a finding about the gene and the disease.
lung carcinoma (17 papers, 2010 to 2024). "PTK7 levels are high in colon, gastric, breast, prostate, and lung cancers and associated with a poor prognosis." (PMID 34502237, 2021). "Moreover, PTK7 expression was associated with a more favorable outcome in gastric or lung cancer." (PMID 25962058, 2015). "We demonstrated that miR‐503 not only regulates EMT but also inhibits migration and invasion by targeting PTK7 in lung cancer cells." (PMID 37212485, 2023). "We found that ectopic expression of miR‐503 resulted in decreased levels of PTK7 mRNA and protein in different lung cancer cells." (PMID 37212485, 2023). "Using in vivo xenograft models of lung cancers with different expression levels of PTK7, systemic delivery of PTK7-CAR2 modified T cells significantly prevented tumor growth and prolonged overall survival of mice." (PMID 34475869, 2021). "These involve genes like MUC16 (CA125) whose levels relate to different stages of NSCLC, and PTK7 that is associated with lymph node metastasis as well as ALK and EGFR mutations in lung cancer." (PMID 33255394, 2020). "Of note, the relative expression of PTK7 in ESCC is comparable to that in lung cancer samples, and PTK7 overexpression was also shown to decrease oncogenic effects in lung squamous cell carcinoma cells." (PMID 29867084, 2018). "Additional studies found migration and invasion promoting functions of PTK7 in lung cancer, intrahepatic cholangiocarcinoma, glioma and prostate cancer." (PMID 26680417, 2015). "Even if PTK7 is upregulated in various cancers including lung cancer, gastric cancer, and acute myolid leukaemia (AML) its function in tumorigenesis and metastasis remains controversial." (PMID 24409301, 2014). "we disclosed the novel roles of miR‐503 and PTK7 in governing lung cancer metastasis." (PMID 37212485, 2023). "MiR‐503 not only suppresses EMT but also targets PTK7 to inhibit invasiveness in lung cancer cells." (PMID 37212485, 2023). "PTK7 is upregulated in many types of cancers including lung cancer." (PMID 37212485, 2023). "Altogether, our results support PTK7 as a therapeutic target suitable for CAR T-cell therapy that could be applied for lung cancers and many other solid cancers with PTK7 overexpression." (PMID 34475869, 2021). "Recently, PTK7 was found to be overexpressed in various human cancers, including epithelial tumors such as gastric, breast, esophagus, biliary duct and lung cancers but also in sarcoma and in hematological malignancies, including acute and chronic myeloid leukemias." (PMID 25962058, 2015). "In addition, based on the fact that PTK7 is pivotal to cohesive migration, as well as our results that PTK7 facilitates migratory and invasive capacities of lung cancer cells, we propose that miR‐503 might modulate collective migration and invasion by inhibiting PTK7." (PMID 37212485, 2023). "Instead, our results suggest that miR‐503 regulates PTK7 expression and EMT in parallel in lung cancer cells." (PMID 37212485, 2023). "In summary, the data presented herein serve as an initial step for future clinical development of PTK7-CAR T-cell therapy safely and efficiently treating PTK7-expressing lung cancer and other malignancies." (PMID 34475869, 2021). "Given the predicted potential and safety of PTK7 as an immunotherapy target, we sought to develop PTK7-specific CAR T-cell therapy for lung cancer and to evaluate its efficacy and safety in in vitro and in vivo preclinical models." (PMID 34475869, 2021). "MiR‐503 is a pleiotropic regulator of lung cancer metastasis, governing both epithelial‐mesenchymal transition (EMT) and EMT‐independent PTK7/FAK signaling.MiR‐503 may represent an attractive target for therapeutic interventions in lung cancer." (PMID 37212485, 2023).
lung carcinoma (continued). "Collectively, miR‐503 is capable of governing EMT and PTK7/FAK signaling independently to control the invasion and dissemination of lung cancer cells, indicating that miR‐503 represents a pleiotropic regulator of cancer metastasis and hence a potential therapeutic target for lung cancer." (PMID 37212485, 2023). "However, we found that PTK7 had no noticeable impact on vimentin levels in lung cancer cells." (PMID 37212485, 2023).
scoliosis (16 papers, 2016 to 2024). A congenital or acquired spinal deformity characterized by lateral curvature of the spine. "This study demonstrated that a significant reduction in motile cilia on ependymal cells is the direct cause of scoliosis in zebrafish ptk7 mutants." (PMID 38086423, 2023). "In conclusion, we identified eight PTK7 variants in our mixed scoliosis cohort, including one frameshift variant (c.464_465delAC) and seven missense variants (c.49C>T, c.353C>T, c.1394A>G, c.1879G>A, c." (PMID 34828397, 2021). "A total of 885 genomes from patients with scoliosis were sequenced and eight PTK7 variants in nine patients were found." (PMID 34828397, 2021). "Mutations in ptk7 or kif6, which affect the formation of ependymal cilia, induce IS-like scoliosis in zebrafish, implicating CSF flow as a crucial regulator of spine stability." (PMID 33251213, 2020). "AIS-like scoliosis develops in loss-of-function mutants of protein tyrosine kinase 7 (ptk7) and kinesin family member 6 in zebrafish." (PMID 26820155, 2016). "Mutations in ptk7, a regulator of Wnt signaling required for cilia motility cause scoliosis." (PMID 35325113, 2022). "Altered expression of PTK7 was initially observed in cancer, but rare missense variants in PTK7 have since been linked to neural tube defects and scoliosis in both humans and animal models, confirming a role in embryonic development." (PMID 36124557, 2022). "Furthermore, PTK7 mutations have recently been implicated in the etiology of neural tube defects and scoliosis." (PMID 28424771, 2017). "Furthermore, mutations in PTK7 have been implicated in scoliosis and human neural tube closure defects, demonstrating its clinical relevance." (PMID 28424771, 2017). "The authors hypothesized that impaired cerebrospinal fluid flow due to abnormal cilia function is most likely the cause of scoliosis in ptk7-deficient zebrafish." (PMID 28424771, 2017). "In addition to neural tube defects, PTK7 has also been implicated in the pathogenesis of scoliosis, a complex genetic disorder characterized by a three-dimensional spinal curvature." (PMID 28424771, 2017). "Interestingly, maternal-zygotic ptk7 (MZptk7) mutant embryos, characterized by complete loss of function, show the scoliosis-like phenotype very early during spine development underlining the importance of the maternal PTK7 in the initial stages of skeletal development." (PMID 31828085, 2019). "The study of zebrafish ptk7 mutants was the first to reveal the connection between abnormal cilia function and scoliosis." (PMID 38086423, 2023). "Zygotic ptk7 (Protein tyrosine kinase-7) mutant zebrafish provide important clues to the etiology of scoliosis and represent a breakthrough in animal model research of AIS." (PMID 34356049, 2021). "Here, we performed WES on the genomes of 885 scoliosis patients, including 583 CS patients and 302 AIS patients, and identified seven missense variants and one frameshift variant in PTK7." (PMID 34828397, 2021). "In zebrafish, recent studies have found that ptk7 mutants also exhibit up-regulation of reactive oxygen species-related genes, suggesting a link between oxidative stressors and scoliosis." (PMID 35155449, 2021). "The ptk7 mutant shows abnormal cilia structure and organization, as well as CSF flow defects, hydrocephalus and scoliosis." (PMID 35155449, 2021). "Treatment with aspirin or N-acetylcysteine lowered the prevalence of scoliosis in ptk7 mutant zebrafish." (PMID 34356049, 2021). "Further, zygotic ptk7 (Zptk7) mutants show late onset spinal curvatures consistent with the idiopathic form of scoliosis." (PMID 28424771, 2017). "Transgenic reintroduction of Ptk7 in motile ciliated lineages prevents scoliosis in ptk7 mutants." (PMID 35761830, 2022). "To date, multiple zebrafish genetic mutants (e.g., ptk7, POC5, kif6) have linked genes involved in cilia and ciliary motility to a progressive scoliosis, giving potential insight into molecular mechanisms that may regulate scoliosis development." (PMID 37239418, 2023).
scoliosis (continued). "Of relevance to developmental PCP signaling, at the onset of scoliosis in zebrafish lacking the vertebrate-specific PCP component Protein tyrosine kinase 7 (Ptk7), TNF is highly expressed and triggers Il-6 expression." (PMID 37589075, 2023). "Interestingly, when juvenile zebrafish ptk7 mutants were treated with the antioxidant agent N-acetylcysteine (NAC), the incidence of scoliosis and the severity of spinal curvature were considerably reduced." (PMID 35155449, 2021). "The connection of PTK7 to scoliosis was further evidenced by the isolation of a novel PTK7 mutation from a single patient suffering from idiopathic scoliosis." (PMID 28424771, 2017). "AIS- and CS-like scoliosis are also observed in zebrafish mutants of ptk7, which regulates both canonical and non-canonical Wnt signaling activity." (PMID 26820155, 2016).
colorectal cancer (14 papers, 2016 to 2025). A primary or metastatic malignant neoplasm that affects the colon or rectum. "A trial for the drug 68Ga-Sgc8, a DNA aptamer targeting protein tyrosine kinase-7 (PTK7) is used for diagnostic purposes in colorectal cancer (status: unknown)." (PMID 33804856, 2021). "Similarly, Ptk7 is expressed in both the developing gut as well as in the adult intestinal epithelium, and there is mounting evidence that Ptk7 dysregulation is associated with the pathogenesis of human gastric and colorectal cancer." (PMID 27438854, 2016). "An increased expression of PTK7 correlates with poor clinical outcomes in acute myeloid leukemia, esophageal squamous cell carcinoma, colorectal cancer, cervical cancer, and thyroid cancer." (PMID 37569547, 2023). "Considering that previous studies have identified the Wnt co-receptor PTK7 on EVs from colorectal cancer cells or FZD10 on sEVs from gastrointestinal cancer cells, the vesicular export of Wnt (co-)receptors seems to be a general mechanism." (PMID 37430307, 2023). "Recently, a small-molecule inhibitor that interferes with the interaction between PTK7 and β-catenin exhibited anticancer effects in colorectal cancer by blocking the Wnt/β-catenin pathway." (PMID 36293051, 2022). "PTK7 expression in colorectal cancer and colorectal adenoma is significantly higher than that in non-tumor mucosa and is significantly correlated with tumor differentiation, lymph node metastasis, and poor survival." (PMID 36293051, 2022). "The study also identifies FZD6, RYK, and PTK7 as candidate receptors for Wnt-11 in colorectal cancer." (PMID 31261741, 2019). "In this review, we focus on two molecules—Protein Tyrosine Kinase 7 (Ptk7) and Mutated in Colorectal Cancer (Mcc)—that do not fit perfectly into the non-canonical pathways described to date and whose roles in cancer are ill defined." (PMID 27438854, 2016). "In colorectal cancer, APC mutant organoids are characterized by upregulated PTK7 expression, suggesting that PTK7 targeting may be beneficial for APC mutant cases." (PMID 39474113, 2024). "This review focuses on two proteins that do not fit the standard non-canonical signaling pathways: Protein tyrosine kinase 7 (Ptk7) and the multiple PDZ domain protein, Mutated in colorectal cancer (Mcc)." (PMID 27438854, 2016).
triple-negative breast carcinoma (11 papers, 2019 to 2025). An invasive breast carcinoma which is negative for expression of estrogen receptor (ER), progesterone receptor (PR), and human epidermal growth factor receptor 2 (HER2). "Protein tyrosine kinase 7 (PTK7), a catalytically defective receptor protein tyrosine kinase, is frequently upregulated in various cancers, including triple-negative breast cancer (TNBC), and is associated with poor clinical outcomes." (PMID 39936972, 2025). "PTK7 promotes the proliferation and migration of triple-negative breast cancer cell lines; conversely, knockdown of PTK7 decreases cell adhesion, migration, and invasion of triple-negative breast cancer cell lines." (PMID 39335176, 2024). "In the case of triple-negative breast cancer, numerous targets have been evaluated, including Trop-2 receptors, zinc transporter LIV-1, PTK-7, NMB glycoproteins, and ephrin receptors." (PMID 35267507, 2022). "For example, patients with high PTK7 expression had lower survival rates than those with low PTK7 expression in ESCC and triple-negative breast cancer (TNBC)." (PMID 36293051, 2022). "It was recently reported that PTK7 is involved in the activation of EGFR and Akt signaling in triple-negative breast cancer cells." (PMID 35216506, 2022).
esophageal squamous cell carcinoma (10 papers, 2016 to 2025). Esophageal squamous cell carcinoma (ESCC) is a type of esophageal carcinoma (EC) that can affect any part of the esophagus, but is usually located in the upper or middle third. "PTK7 is an important modulator of tumorigenesis in adult tissues and is upregulated in esophageal squamous cell carcinoma (ESCC), colorectal cancer, and other cancers." (PMID 35216506, 2022). "We knocked down PTK7 in two esophageal squamous cell carcinoma cell lines, TE-5, and TE-9, by siRNA, and evaluated cell proliferation, apoptosis, and migration ofPTK7-defective cells." (PMID 28545451, 2017). "In summary, we have provided in vitro evidence that PTK7 promotes proliferation and migration of esophageal squamous cell carcinoma cells." (PMID 28545451, 2017). "In the current study, we found PTK7 plays a significant role in promoting tumor cell growth in esophageal squamous cell carcinoma cell lines." (PMID 28545451, 2017). "PTK7 achieves its oncogenic function in esophageal squamous cell carcinoma partially through the negative regulation of apoptosis." (PMID 28545451, 2017). "PTK7 is upregulated in esophageal squamous cell carcinoma (ESCC), colorectal cancer, and other cancers." (PMID 27689325, 2016). "One mechanism by which PTK7 might exert these diverse functions was discovered in esophageal squamous cell carcinoma (ESCC) cells." (PMID 34502237, 2021). "This prompted us to test if PTK7 is also regulated in esophageal squamous cell carcinoma." (PMID 28545451, 2017). "Interestingly, in both studies, PTK7 is expressed 1.5-fold or higher in esophageal squamous cell carcinoma than in the normal esophageal tissues, and the difference is statistically significant." (PMID 28545451, 2017). "Importantly, PTK7 achieve its oncogenic function in human esophageal squamous cell carcinoma partially through the attenuation of apoptosis." (PMID 28545451, 2017). "In light of overexpression of PTK7 in the clinical tumor samples of human esophageal squamous cell carcinoma, we further knocked down its level in two esophageal carcinoma cell lines, TE-5 and TE-9, by siRNA, of which the knockdown specificity has been confirmed." (PMID 28545451, 2017). "In this study, we found that PTK7 plays an oncogenic role in esophageal squamous cell carcinoma." (PMID 28545451, 2017). "Studies of PTK7 in esophageal cancer have mainly focused on esophageal squamous cell carcinoma (ESCC)." (PMID 39474113, 2024). "PTK7 is associated with proliferation, migration, and invasiveness, and activates FGFR1 independently of FGF in esophageal squamous cell carcinoma (ESCC) cells." (PMID 37569547, 2023). "PTK7 is a catalytically defective receptor protein tyrosine kinase upregulated in various cancers, including esophageal squamous cell carcinoma (ESCC)." (PMID 36293051, 2022). "More interestingly, disruption of PTK7 further slowed down cellular migration in vitro, during which the epithelial-mesenchymal transition marker gene E-cadherin was upregulated, suggesting PTK7 may promote metastasis of esophageal squamous cell carcinoma." (PMID 28545451, 2017). "Importantly, more siPTK7 cells undergo apoptosis than the controls, and major apoptotic regulators are upregulated in the PTK7-knockdown cells, suggesting PTK7 may be a major regulator of apoptosis in esophageal squamous cell carcinoma." (PMID 28545451, 2017). "Protein tyrosine kinase 7 (PTK7), a catalytically defective receptor protein tyrosine kinase, is upregulated in tumor tissues and cell lines of esophageal squamous cell carcinoma (ESCC)." (PMID 35216506, 2022).
esophageal squamous cell carcinoma (continued). "Protein tyrosine kinase 7 (PTK7), a member of the catalytically defective receptor protein tyrosine kinase family, is upregulated in various cancers including esophageal squamous cell carcinoma (ESCC)." (PMID 27689325, 2016). "Additionally, PTK7 promotes proliferation, migration, and invasiveness of esophageal squamous cell carcinoma (ESCC) cells by activating fibroblast growth factor receptor 1 (FGFR1) and contributes to epidermal growth factor receptor (EGFR)/Akt signaling in TNBC cells." (PMID 39936972, 2025).
acute myeloid leukemia (9 papers, 2010 to 2024). Acute myeloid leukemia (AML) is a group of neoplasms arising from precursor cells committed to the myeloid cell-line differentiation. "An earlier high-throughput analysis of genome-wide RTK expression in human cancers identifies PTK7 as overexpressed in acute myeloid leukemia (AML)." (PMID 39474113, 2024). "Oncogenic functions of PTK7, including resistance to chemotherapy, have been reported for various carcinomas and acute myeloid leukemia (AML)." (PMID 30984612, 2019). "PTK7 is expressed in acute myeloid leukemia, where it promotes cell migration and leads to a poor clinical outcome." (PMID 26680417, 2015). "While PTK7 expression is upregulated in various cancers including colon, lung, gastric, breast cancer, and acute myeloid leukemia, PTK7 is also considered as a gene involved in the initiation of tumorigenesis." (PMID 24409301, 2014). "PTK7 also correlates significantly with clinical parameters in acute myeloid leukemia." (PMID 39474113, 2024). "We previously found that PTK7 expression enhances drug resistance in acute myeloid leukemia cells." (PMID 25962058, 2015).